KRABD1 (KRAB domain containing 1)
Synonyms: KRBOX1
Tractability: No criterion of Open Targets' tractability assessment is met for any kind of drug.
Gene: Protein-coding gene on chromosome 3 (42,936,386 to 42,942,792, forward strand). Ensembl gene ENSG00000240747.
Subcellular location (Human Protein Atlas): Nucleoplasm; Golgi apparatus
Gene Ontology:
Molecular function: DNA-binding transcription repressor activity, RNA polymerase II-specific; RNA polymerase II cis-regulatory region sequence-specific DNA binding
Biological process: negative regulation of transcription by RNA polymerase II; regulation of DNA-templated transcription
Cellular component: nucleus
Genetic constraint (gnomAD): Loss-of-function variants: 4 observed, 4.26 expected, observed/expected ratio (o/e) 0.94, 90% interval 0.45 to 1.8. That is too few expected variants to judge how well the gene tolerates losing a copy. Missense variants: 102 observed, 80.23 expected, observed/expected ratio (o/e) 1.27, 90% interval 1.08 to 1.5. Synonymous variants: 34 observed, 32.92 expected, observed/expected ratio (o/e) 1.03, 90% interval 0.79 to 1.38.
Homologues: Orthologues: chimpanzee KRBOX1 (100% identical), rabbit KRBOX1 (62% identical), Caenorhabditis elegans F57C9.4 (13% identical), Caenorhabditis elegans K09F6.6 (11% identical), zebrafish si:ch211-89o9.6 (10% identical), Drosophila melanogaster CG9609 (8% identical), Caenorhabditis elegans F49C5.3 (5% identical), Caenorhabditis elegans M04C9.4 (5% identical), Caenorhabditis elegans Y48A6B.8 (5% identical), mouse Zfp65 (5% identical), Caenorhabditis elegans K09F6.15 (5% identical), Caenorhabditis elegans T11F9.7 (3% identical), and 1 more. Paralogues in human: ZNF532 (28% identical), ZNF200 (9% identical).
Diseases named in the same sentence as KRABD1 in open-access papers:
KRABD1 is named in the same sentence as 2 diseases in open-access papers, as found by Europe PMC text mining. Sharing a sentence is not in itself a finding about the gene and the disease.
KRABD1 shares sentences with these, for which no sentence is quoted: asthma (1 paper); bladder cancer (1).